E2F1 (E2F transcription factor 1)
Diseases named in the same sentence as E2F1 in open-access papers (continued):
Sharing a sentence is not in itself a finding about the gene and the disease.
hypopharyngeal carcinoma (3 papers, 2022 to 2024). Carcinoma, predominantly squamous cell, arising from the epithelial cells of the hypopharynx. "E2F1-mediated MNX1-AS1 expression was implicated in the anti-tumor effect of acRoots on hypopharyngeal carcinoma." (PMID 35152841, 2022). "Expression of E2F1 was positively associated with MNX1-AS1 in hypopharyngeal carcinoma." (PMID 35152841, 2022). "Overexpression of E2F1 attenuated Actinidia chinensis Planch root extract-induced decrease in MNX1-AS1 expression in hypopharyngeal carcinoma cells." (PMID 35152841, 2022). "FaDu with acRoots incubation were transfected with pcDNA-E2F1 to detect the effect of acRoots/E2F1 on hypopharyngeal carcinoma growth." (PMID 35152841, 2022). "FaDu was also transfected with pcDNA-E2F1, shE2F1, pcDNA-MNX1-AS1, or shMNX1-AS1 to investigate the effects of E2F1 or MNX1-AS1 on hypopharyngeal carcinoma." (PMID 35152841, 2022). "Overexpression of E2F1 attenuated acRoots-induced decrease in MNX1-AS1 in hypopharyngeal carcinoma cells." (PMID 35152841, 2022). "In conclusion, acRoots exerted tumor-suppressive role in hypopharyngeal carcinoma through inhibition of E2F1-mediated MNX1-AS1." (PMID 35152841, 2022). "Lastly, administration with acRoots retarded in vivo hypopharyngeal carcinoma growth through down-regulation of E2F1-mediated MNX1-AS1." (PMID 35152841, 2022). "Our results showed that transcriptional factor, E2F1, was reduced in hypopharyngeal carcinoma tissues and cells post acRoots incubation." (PMID 35152841, 2022). "In this study, we hypothesized that acRoots might suppress progression of hypopharyngeal carcinoma through regulation of E2F1." (PMID 35152841, 2022). "The overexpression of E2F1 counteracted with the suppressive effects of acRoots on cell migration and invasion in FaDu, revealing that acRoots suppressed hypopharyngeal carcinoma progression through down-regulation of E2F1." (PMID 35152841, 2022). "However, the effects of E2F1/MNX1-AS1 on the progression of hypopharyngeal carcinoma post acRoots incubation should be investigated in further research." (PMID 35152841, 2022). "Therefore, acRoots exerted anti-tumor effect against hypopharyngeal carcinoma through down-regulation of E2F1." (PMID 35152841, 2022). "Thirdly, E2F1 (E2F Transcription Factor 1) and lncRNA MNX1-AS1 (MNX1 antisense RNA 1) were up-regulated in hypopharyngeal carcinoma tissues, and reduced in hypopharyngeal carcinoma cells post acRoots incubation." (PMID 35152841, 2022).
injury (3 papers, 2016 to 2023). Damage inflicted on the body as the direct or indirect result of an external force, with or without disruption of structural continuity. "SIRT1 regulated oligodendrocyte regeneration via deacetylating retinoblastoma in the Rb/E2F1 complex, leading to E2F1 dissociation in neonatal brain injury mice." (PMID 36111151, 2022). "On the basis of our findings that higher level of unbound E2F1 could be detected in white matter progenitors after HX, we propose a molecular mechanism underlying OPC proliferation and pool expansion induced by neonatal brain injury." (PMID 27991597, 2016).
invasive breast carcinoma (3 papers, 2015 to 2022). A carcinoma that infiltrates the breast parenchyma. "The data from Starbase illustrated that E2F1 was highly expressed in breast invasive cancer." (PMID 35293275, 2022). "In these studies, E2F1 expression was only slightly or not significantly induced in tumor tissue relative to matched normal tissue, with the only exception being the invasive breast cancer study in which a 2.16-fold up-regulation of Pak1 correlated with a 2.7-fold up-regulation of E2F." (PMID 26555075, 2015).
kidney cancer (3 papers, 2013 to 2023). Primary or metastatic malignant neoplasm involving the kidney. "In kidney cancer, E2F1 could enhance the metastatic potential of tumor cells through the activation of matrix metalloproteinase (MMP) 2 and MMP9." (PMID 37077419, 2023). "Notably, nested PCR with E2F1/E5R1 showed that all 9 kidney cancer patients expressed E5 in their N tissues, of them 3 (Ki#1, 7, 8) lost E5 expression in their T tissues." (PMID 23614038, 2013).
mesothelioma (3 papers, 2011 to 2024). A usually malignant and aggressive neoplasm of the mesothelium which is often associated with exposure to asbestos. "Given that WDPMP is a rare sub-type of mesothelioma, it is of interest to extrapolate E2F1's role to the more prevalent MPM." (PMID 21955916, 2011). "Therefore, it is likely that in case of mesothelioma E2F1 expression gets activated by genetic deletion of p16 or by PRC2-mediated repression." (PMID 38519707, 2024).
Myocardial fibrosis (3 papers, 2021 to 2025). "We speculate that E2F1 is involved in the process of myocardial fibrosis." (PMID 40615041, 2025).
oral cancer (3 papers, 2020 to 2023). "A study found that overexpression of KDM1A induces E2F1 signaling via histone demethylation and promotes cell proliferation in oral cancer and that inhibition of KDM1A reduces E2F1 signaling, implying an oncogenic role of KDM1A in oral cancer." (PMID 34220955, 2021).
osteoarthritis (3 papers, 2016 to 2024). A noninflammatory degenerative joint disease occurring chiefly in older persons, characterized by degeneration of the articular cartilage, hypertrophy of bone at the margins and changes in the synovial membrane. "In primary control and osteoarthritis chondrocytes, real time RT-PCR was used to measure the mRNA expression levels of candidate genes under E2F1 transcriptional control." (PMID 27802335, 2016). "Previous research on osteoarthritis shows that E2F1 could boost osteoclastogenesis and induce inflammation." (PMID 33691763, 2021). "Results from the present study reveal, for the first time, that PITX1 is a direct target of E2F1, and other targets may also be regulated in a similar manner during the progression of osteoarthritis." (PMID 27802335, 2016).
Sepsis (3 papers, 2022 to 2024). Sepsis is defined as life-threatening organ dysfunction caused by a dysregulated host response to infection. "The bioinformatics study demonstrated that E2F1 was a regulator of differentially expressed genes associated with ferroptosis in sepsis patients." (PMID 38187112, 2023). "The transcriptional response of the coagulation cascade was diminished in E2F1-deficient mice, suggesting that disseminated intravascular coagulation may be a consequence of uncontrolled sepsis." (PMID 38187112, 2023). "The transcription factor E2F1, a member of the E2F family, exerts regulatory control over diverse biological processes and plays pivotal roles in numerous diseases, including cancers, obesity, inflammation, and sepsis." (PMID 38187112, 2023). "HDAC5 inhibitor LMK-235 suppressed inflammation in sepsis via the ghrelin/E2F1/NF-κB axis." (PMID 38187112, 2023). "Furthermore, our study creatively identified the potential of E2F1/NF-κB signaling to inhibit sepsis-induced intestinal dysfunction in vivo." (PMID 38187112, 2023). "We predicted that the XIST−hsa-let-7b-5p−TGFBR1/DUSP1 ceRNA network and transcription factor E2F1 might be important regulators of sepsis." (PMID 36188533, 2022).
Stroke (3 papers, 2022 to 2025). Sudden impairment of blood flow to a part of the brain due to occlusion or rupture of an artery to the brain. "E2F1/4 is involved in the regulation of CITED2 expression in neurons after stroke-related injury." (PMID 38003393, 2023). "E2F family members (E2F1 and E2F4) are involved in the regulation of CITED2 expression in neurons after stroke-related injury." (PMID 36358994, 2022).
testicular cancer (3 papers, 2019 to 2021). A primary or metastatic malignant neoplasm that affects the testis. "Even though it remains to be further elucidated which molecular pathways are involved in the upregulation of E2F1 protein, this finding strongly suggests a contribution of germline E2F1 copy numbers in rendering this individual particularly susceptible to cancer of the testis." (PMID 31142321, 2019). "Consistent with this, germline duplications of E2F1 gene have been recently observed in testicular cancer patients, suggesting a potential role of E2F1 copy number variations (CNVs) in the development of this type of cancer." (PMID 31142321, 2019). "We previously reported germline gains of E2F1 in men with testicular cancer." (PMID 31142321, 2019). "In summary, cordycepin inhibited FGF9-induced testicular tumor growth by suppressing the ERK1/2, Rb/E2F1, cell cycle pathways, and the expressions of FGFR1-4 proteins, suggesting that cordycepin can be used as a novel anticancer drug for testicular cancers." (PMID 33172093, 2020).
atherosclerosis (2 papers, 2016 to 2022). A disease characterized by the build-up of fatty material and calcium deposition in the arterial wall resulting in partial or complete occlusion of the arterial lumen. "We found significant enrichment of four TF binding sites (adjusted p-value <0.05), including binding sites of E2F1, a gene/protein with a potential role in atherosclerosis and coronary heart disease (CHD)." (PMID 27884142, 2016). "TFs included E2F1 with prior evidence of a function in processes relating to atherosclerosis and CHD, connecting genes for which CpG methylation changed with oxidative stress to CVD." (PMID 27884142, 2016).
autoimmune disease (2 papers, 2018 to 2025). A disorder resulting from loss of function or tissue destruction of an organ or multiple organs, arising from humoral or cellular immune responses of the individual to their own tissue constituents. "The role of E2F1 in autoimmune diseases has been associated with cell cycle regulation and apoptosis." (PMID 39902022, 2025). "Antimetabolites are a class of drugs used for inducing medical abortions and treating cancers and autoimmune diseases through halting of cell cycles, while E2F1 and E2F4 are well-known regulators of cell cycles." (PMID 29325558, 2018). "In addition, therapies targeting the E2F1 signaling pathway may offer promising new approaches for the treatment of autoimmune diseases such as MS." (PMID 39902022, 2025). "Finally, therapies targeting E2F1 could open new avenues for the treatment of MS and related autoimmune diseases." (PMID 39902022, 2025).
Azoospermia (2 papers, 2016 to 2023). Absence of any measurable level of sperm,whereby spermatozoa cannot be observed even after centrifugation of the semen pellet. "In the man with azoospermia, we found elevated E2F1 and HOXB9 gene expressions when compared with his brother, suggesting that the increased RNA expression of these genes could influence sperm production." (PMID 37492809, 2023). "In the study of nonobstructive azoospermia, 4 patients with microduplications and 4 with microdeletions of E2F1 were identified among 110 affected individuals, but not among 78 fertile controls." (PMID 27769252, 2016).
bronchogenic carcinoma (2 papers, 2005 to 2006). A lung carcinoma arising from the bronchial epithelium. "Transcript abundance (TA) levels of E2F1, p73α, and p21 in normal bronchial epithelial cells (BEC) (N = 18) and bronchogenic carcinoma (BC) tissues (N = 21) were measured by StaRT-PCR." (PMID 16014176, 2005). "In this study, we provide strong empirical and experimental evidence that in human bronchogenic carcinoma, p21 transcription is regulated by p73 but, in contrast to other cell types, not directly by E2F1." (PMID 16014176, 2005).
carcinoma in situ (2 papers, 2006 to 2014). "Other immunohistochemical studies conducted in our lab on sections from excised human testicular tumors have demonstrated that E2F-1 is strongly expressed in carcinoma in situ (data not submitted), supporting its role in initiating proliferation of SSCs in testis." (PMID 17147820, 2006).
cardiac hypertrophy (2 papers, 2011 to 2024). "E2F-1 and E2F-3 are shown to be important regulators for cell proliferation, particularly E2F-1, which has been demonstrated to improving myocardial hypertrophy." (PMID 38008859, 2024). "This is of particular relevance, since cardiac hypertrophy and chronic heart failure have both been related to inflammatory processes in the myocardium and we have also demonstrated that triggering E2F1 in human cardiac cells partially abrogates cytokine secretion." (PMID 21625432, 2011).
colitis (2 papers, 2013 to 2022). Inflammation of the colon. "Meanwhile, transcription factors JUN, E2F1, and GATA2 have been reported to be closely related to the occurrence and development of colitis-associated tumors." (PMID 35733095, 2022). "Moreover, DSS-induced colitis increased RB phosphorylation and inactivation in the colonic mucosa, resulting in increased proliferation through the E2F1 pathway." (PMID 23967107, 2013).
Crohn disease (2 papers, 2017). A gastrointestinal disorder characterized by chronic inflammation involving all layers of the intestinal wall, noncaseating granulomas affecting the intestinal wall and regional lymph nodes, and transmural fibrosis. "In this study, we analyze the expression and modulation of CyD1 and E2F1 in colon explants from Crohn’s disease (CD) patients." (PMID 30050877, 2017). "The aim of this study is to analyze the expression of CyD1 and E2F1 in colon tissues specimens from patients affected with Crohn’s disease after culture, and the efficacy of purposely formulated and produced siRNA vectors to deliver CyD1 and E2F1 siRNAs able to control inflammation progression." (PMID 30050877, 2017).
diabetic kidney disease (2 papers, 2013 to 2022). Progressive kidney disorder caused by vascular damage to the glomerular capillaries, in patients with diabetes mellitus. "TGFβ and CCN2 attenuate CREB and augment E2F1 transcriptional activation with the likely effect of altering actin cytoskeletal and cell growth/hypertrophic gene activity with implications for cell dysfunction in diabetic kidney disease." (PMID 23902294, 2013).
endothelial dysfunction (2 papers, 2021 to 2025). In vascular diseases, endothelial dysfunction is a systemic pathological state of the endothelium (the inner lining of blood vessels) and can be broadly defined as an imbalance between vasodilating and vasoconstricting substances produced by (or acting on) the endothelium. "On the other hand, E2f1 downregulation prevents endothelial dysfunction induced by high glucose in cultured HUVEC, and E2F1 depletion in bone marrow progenitor cells results in increased mitochondrial respiration and enhanced endothelial differentiation." (PMID 40761766, 2025).
fibrosis (2 papers, 2021 to 2025). the formation of excess fibrous connective tissue in an organ or tissue in a reparative or reactive process. "Anti-E2F1 might be a better strategy for cardiac fibrosis than intervening TGF-β–Smad2/3 signaling pathway directly." (PMID 34521301, 2021).
heart failure (2 papers, 2011 to 2021). Inability of the heart to pump blood at an adequate rate to meet tissue metabolic requirements. "Since E2F1 plays an important role in cardiac myocyte growth and is also involved in metabolism regulation through PDK4 modulation, targeting this transcription factor could provide us with an effective therapy for treating detrimental left ventricular hypertrophy leading to heart failure." (PMID 21625432, 2011).
hyperlipidemia (2 papers, 2020). "This study presented important evidence to support that E2F1 also serves as a promoter of hepatic secretion of VLDL and hyperlipidemia by modulating miR-378a-3p-SORT1 axis." (PMID 32226531, 2020).
Hypertension (2 papers, 2020 to 2021). The presence of chronic increased pressure in the systemic arterial system. "E2F1 and ENOS were shown to cooperate with each other in the treatment of hypertension." (PMID 35003234, 2021).
infertile (2 papers, 2015 to 2018). "Therefore, low CDC25A expression in infertility may be caused by mutations/polymorphisms that affect the family of DAZ, E2F-1 and c-myc genes in the metabolic cascade or other factors that interfere with mRNA production or stability." (PMID 30009144, 2018).
infiltrating ductal carcinoma (2 papers, 2008 to 2018). "The hypothesized repression of telomerase activity in infiltrating ductal carcinoma cells via E2F-1 repressor proteins is supported by significant hTERT repression in both HCC1937 and HCC1599 cells." (PMID 18366791, 2008).
insulin-dependent diabetes (2 papers, 2017 to 2020). "E2f1/E2f2 mutant mice show severe exocrine atrophy of pancreatic β cells, primarily resulting from E2F1 mutation, which leads to insulin-dependent diabetes." (PMID 29176962, 2017).
ischemia (2 papers, 2016 to 2021). A hypoperfusion of the BLOOD through an organ or tissue caused by a PATHOLOGIC CONSTRICTION or obstruction of its BLOOD VESSELS, or an absence of BLOOD CIRCULATION. "We previously reported that E2F1 binds to the VEGF promoter in the ischemia myocardium." (PMID 27490344, 2016).
ischemic stroke (2 papers, 2022 to 2023). A stroke disorder caused by obstruction of blood flow to the brain, due to thrombotic (local blood clot formation) or embolic (due to a blood clot or other material traveling from another site) event.
keloid (2 papers, 2007 to 2024). An irregularly shaped, elevated mark on the skin caused by deposits of excessive amounts of collagen during wound healing. "The downregulation of FOXF1 and LPAR1 in keloid patients could be caused by the inactivation of E2F1 and SP1 due to mutations or other factors, or by the effect of the three miRNAs." (PMID 38444850, 2024).
latent infection (2 papers, 2012 to 2025). "Our previous global transcriptomic analysis revealed that E2F1 expression is transcriptionally activated during EBV latent infection in naïve B-lymphocytes but suppressed during reactivation into lytic-cycle replication." (PMID 40773523, 2025). "Although the underlying mechanism is still incomplete, it is conceivable that during latent infection EBV critically modulates E2F1 levels to mitigate DNA damage response and promote efficient B-cell transformation." (PMID 40773523, 2025). "In contrast to latent infection, there are contradictory reports available on E2F1 regulations during EBV lytic replication." (PMID 40773523, 2025). "The inhibitory effect of EBNA3C on E2F1 mediated transcriptional activity led us to further investigate the basal expression levels of E2F1 both in primary as well as in latent infection model systems." (PMID 22438805, 2012). "Our results also show that EBNA3C represses E2F1 mediated transcriptional activity by blocking the E2F1-DNA binding ability in latent infection using EBNA3C knockdown LCLs as confirmed by endogenous ChIP experiments." (PMID 22438805, 2012). "E2F1 functions are implicated in EBV pathogenesis, particularly in the context of latent infection." (PMID 40773523, 2025). "To further determine whether these changes also correlated in latent infection, we assessed both transcript and protein levels of E2F1 and its related apoptotic markers in EBNA3C knockdown LCLs." (PMID 22438805, 2012). "Given its role as a robust DNA-binding transcription factor and the observed differential expressions between EBV latent infection and lytic cycle reactivation, we hypothesized that E2F1 directly interacts with the EBV genome to regulate viral gene transcription." (PMID 40773523, 2025). "In contrast to latent infection in B-lymphocytes, our data demonstrated that EBV lytic cycle replication transcriptionally repressed E2F1 expression in both B-lymphocyte and epithelial cell background." (PMID 40773523, 2025).